KIF6 (kinesin family member 6)
Diseases named in the same sentence as KIF6 in open-access papers (continued):
Sharing a sentence is not in itself a finding about the gene and the disease.
Aortic dissection (1 paper, 2023). Aortic dissection refers to a tear in the intimal layer of the aorta causing a separation between the intima and the medial layers of the aorta. "In the present study, we have augmented the patient number substantially and have investigated once again the association between the KIF6 719Arg variant and the incidence of aortic dissection." (PMID 36833179, 2023). "We have found, in this large sample of thoracic aortic aneurysm patients, that the KIF6 719Arg genetic variant confers substantially increased risk of aortic dissection." (PMID 36833179, 2023). "In a preliminary investigation, we were able to identify an association between the same KIF6 variant and the likelihood of thoracic aortic aneurysm patients suffering an aortic dissection." (PMID 36833179, 2023). "Specifically, carriers of the KIF6 719Arg variant were found to have a two-fold increase in susceptibility to aortic dissection (OR 2.14, confidence interval (CI) 1.18–3.9)." (PMID 36833179, 2023). "We have demonstrated important associations of the KIF6 719Arg variant with aortic dissection, which we hope will enhance prediction and patient triage." (PMID 36833179, 2023). "In our initial pilot study of KIF6 719Arg’s impact on aortic dissection, we stated: “If the association of the KIF6 719Arg variant with thoracic aortic dissection is further confirmed, this variant could be useful in assessing thoracic aortic dissection risk”." (PMID 36833179, 2023). "We feel that this study raises the possibility that KIF6 719Arg variant status may serve as a useful clinical predictor for the likelihood of aortic dissection." (PMID 36833179, 2023). "Patients dying upon initial presentation from aortic dissection are generally not included in our KIF6 analysis, as KIF6 719Arg testing, a specialized laboratory test, would not have been a priority or a feasibility under such urgent circumstances." (PMID 36833179, 2023).
Azoospermia (1 paper, 2023). Absence of any measurable level of sperm,whereby spermatozoa cannot be observed even after centrifugation of the semen pellet. "Based on Sanger sequencing data, the frequencies observed in our cases and controls suggest that KIF6 mutations account for 60% of azoospermia cases and 50% of oligospermia cases, respectively." (PMID 37895049, 2023). "The SPATA16, CFTR, KIF6, STPG2, and DRC7 mutations are associated with male infertility, specifically azoospermia, and a further examination of this genetic function is required." (PMID 37895049, 2023). "Interestingly, in our Taiwan study, the KIF6 SNP (rs2273063) and STPG2 (rs2903150) co-occur in an 80% mutation rate in azoospermia and oligozoospermia patients with 20% MAF in ordinary men of Taiwan by Sanger sequencing." (PMID 37895049, 2023).
cardiomyopathy (1 paper, 2022). A disease of the heart muscle or myocardium proper. "These include a high positive selection on KAI14, KIF6 (both indicated in cardiomyopathy), and PDE11A (vasoregulation), as well as pathway enrichments for the renin-angiotensin system and the endothelin-1 pathway, identified in both WedAR and dN/dS analyses." (PMID 35177770, 2022). "The three genes under the greatest positive selection in the dN/dS analysis are implicated in either cardiomyopathy (RAI14, KIF6) or vasoregulation (PDE11A)." (PMID 35177770, 2022).
dissection (1 paper, 2023). The separation and isolation of tissues for surgical purposes, or for the analysis or study of their structures. "Nonetheless, within the limited context of our thoracic aortic patient group, KIF6 719arg variant status appears to confer a substantial superimposed vulnerability to aortic dissection." (PMID 36833179, 2023). "In a pilot study, we found that a common KIF6 Trp719Arg variant increased the propensity of thoracic aortic aneurysms (TAA) to suffer dissection (AD)." (PMID 36833179, 2023).
dyslipidemia (1 paper, 2017). "In conclusion, our results showed important associations between HMG-CoA rs3846662 and KIF6 rs20455 and lipid phenotypes, which may have an influence on dyslipidemia-related events." (PMID 29295555, 2017). "Our results showed associations between HMG-CoA rs3846662 and KIF6 rs20455 and lipid phenotypes, which may have an influence on dyslipidemia-related events." (PMID 29295555, 2017).
Hypercholesterolemia (1 paper, 2017). An increased concentration of cholesterol in the blood. "This study was performed to evaluate whether individuals’ polymorphisms in HMG-CoA and KIF6 genes are independently associated with hypercholesterolemia, other lipid-associated traits, and statin response in unselected individuals enrolled in the Brisighella heart study." (PMID 29295555, 2017).
infertile (1 paper, 2023). "Sanger sequencing was employed to confirm the presence of SNPs on KIF6 and STPG2, facilitating a gene comparison between infertile and fertile men." (PMID 37895049, 2023).
Intellectual disability (1 paper, 2018). "Here, we identified a homozygous truncating mutation in KIF6 in a child displaying neurodevelopmental defects and intellectual disability." (PMID 30475797, 2018). "This is supported by several lines of evidence including the discovery of a novel nonsense-mutation of KIF6 in a child with intellectual disability and megalencephaly and underscored by functional analysis in both mouse and zebrafish Kif6 mutant models." (PMID 30475797, 2018). "Here, we report a homozygous one base-pair deletion, c.1193delT (p.Leu398Glnfs*2), in the Kinesin Family Member 6 (KIF6) gene in a child displaying neurodevelopmental defects and intellectual disability." (PMID 30475797, 2018). "Finally, we propose that KIF6 represents a novel locus for understanding mechanisms of neurological development and intellectual disability in humans." (PMID 30475797, 2018).
male infertility (1 paper, 2023). The inability of the male to effect fertilization of an ovum after a specified period of unprotected intercourse. "Consequently, when evaluating its potential relevance to male infertility, it is less representative compared to KIF6 due to its already elevated mutation rate in ordinary men." (PMID 37895049, 2023). "Both DRC7 and KIF6 stand out as promising candidates for meaningful genetic testing in the context of male infertility." (PMID 37895049, 2023). "In this study, an Ampiseq targeted NGS panel and Illumina TruSeq WES were both used to pinpoint six specific genes (KIF6, DRC7, STPG2, SPATA16, CFTR, CMTM2) that play a role in MT association and spermiogenesis, which are crucial factors in understanding the causes of male infertility." (PMID 37895049, 2023). "Our experimental results have pinpointed evidence for a potential link between genetic variations in the KIF6, DRC7, and STPG2 genes with male infertility." (PMID 37895049, 2023).
cardiovascular disease (7 papers, 2011 to 2018). "Many studies suggest that there is a relationship between the rs20455 KIF6 gene variant (c.2155T> C, Trp719Arg) and a lower risk of cardiovascular disease in patients being treated with statins." (PMID 30304062, 2018). "We hypothesised that if loss of Kif6 function was associated with cardiovascular disease, then mice with a deleterious mutation in the Kif6 motor domain may exhibit defects in cardiac physiology." (PMID 23355886, 2013). "Since tHcy and CRP have demonstrated associations with cardiovascular disease and AD, we sought to investigate whether KIF6 719Arg carrier status is associated with tHcy and CRP in a group of clinically diagnosed AD and aMCI patients." (PMID 24455405, 2013). "One possible explanation is that the KIF6 719Arg allele may increase the risk of cardiovascular disease (CVD), and that treatment with a statin may ameliorate this increased risk through a pleiotropic effect." (PMID 22216121, 2011). "Cardiovascular disease (CVD) risks were assigned by the Framingham equation and events distributed among KIF6 Trp719Arg genotypes according to published prospective studies." (PMID 21435211, 2011).
KIF6 also shares sentences with these, for which no sentence is quoted: tumor (2 papers); acute myocardial infarction (1); cancer (1); central obesity (1); dementia (1); dyslipidaemia (1); endothelial dysfunction (1); epilepsies (1); idiopathic scoliosis (1); ischemic stroke (1); megalencephaly (1); oligospermia (1); pancreatic cancer (1); thoracic aortic aneurysm (1); type 2 diabetes mellitus (1).